EGFR (epidermal growth factor receptor)
Diseases named in the same sentence as EGFR in open-access papers (continued):
Sharing a sentence is not in itself a finding about the gene and the disease.
non-small cell lung carcinoma (continued). "Furthermore, the growth of renal cell carcinoma, glioblastoma multiforme, as well as non-small-cell lung cancer, pancreatic, colon, and breast cancers were synergistically reduced when EGFR inhibitors were combined with the mTOR inhibitor rapamycin." (PMID 18797454, 2008). "For example, GCN can be elevated in cancer cells as demonstrated in the epidermal growth factor receptor (EGFR) gene in patients with non-small cell lung cancer and also higher copy number of CCL3L1 has been associated with susceptibility to human HIV infection." (PMID 19812787, 2008). "Somatic mutations of EGFR tyrosine kinase domain are associated with exquisite sensitivity to EGFR-tyrosine kinase inhibitors erlotinib and gefitinib in non-small cell lung cancer (NSCLC), but such mutations are rare or absent in CRC." (PMID 18544172, 2008). "EGFR-targeted therapeutics have been explored in a large number of human malignancies and have shown clinical activity in subsets of patients with non-small cell lung cancer (NSCLC), glioblastoma, squamous cell carcinomas of the head and neck, colorectal carcinoma, and certain other malignancies." (PMID 17973575, 2007). "Of particular interest, EGFR mutation is the first molecular abnormality that is more frequent in nonsmoking patients with non-small cell lung cancer (NSCLC)." (PMID 17325698, 2007). "In the future, EGFR-targeted therapeutics may be routinely used in the treatment of non-small cell lung cancers, including SCCs." (PMID 17533397, 2007). "In conclusion, cytology specimens could be useful for analysing the EGFR status in the majority of patients with non-small-cell lung cancer to determine whether they are likely to benefit from gefitinib treatment." (PMID 17047654, 2006). "The tyrosine kinase inhibitor, gefitinib, is targeted against EGFR and is being used in clinical trials with objective responses of antitumour activity being noted in non-small-cell lung cancer, squamous cell carcinoma of the head and neck and in hormone-refractory prostate cancer." (PMID 15083203, 2004). "We investigated whether EGFR expression levels could predict for response to gefitinib in patients with advanced non-small-cell lung cancer (NSCLC), who received gefitinib (250 mg day−1) as part of a worldwide compassionate-use programme." (PMID 15187994, 2004). "Our systematic evaluation of the effect of ginsenoside Rg3 in combination with EGFR-TKI in the treatment of non-small cell lung cancer also further validated that ginsenoside Rg3 may be more sensitive for patients with EGFR mutant phenotype and that EGFR may be an important target for its action." (PMID 40732366, 2025). "Mutations in SMARCA4 have been shown to co-exist with KRAS mutations but are mutually exclusive from common targetable non-small cell lung carcinoma (NSCLC) oncogenes, including EGFR, ALK, MET, ROS-1, and RET." (PMID 40406754, 2025). "EGFR tyrosine kinase inhibitors (EGFR-TKIs) block the cellular functions mediated by EGFR kinase signaling in non-small cell lung cancer, but they also activate inactive EGFR in autophagy, which may provide a survival advantage and induce TKI resistance in cancer." (PMID 40231269, 2025). "In addition to significant benefit in treatment-naïve non-small cell lung cancer (NSCLC) with non-resistant EGFR mutations, afatinib has shown notable efficacy in tumors, including PDA, harboring neuregulin (NRG1) fusions, as seen in the basket study TAPUR." (PMID 40507311, 2025). "CEA stands as a highly researched and confirmed serum indicator of non-small cell lung cancer (NSCLC) patients, beneficial in diagnosing, predicting outcomes, and evaluating treatments, especially in individuals with mutations in the epidermal growth factor receptor (EGFR)." (PMID 40712559, 2025).
non-small cell lung carcinoma (continued). "The efficacy, safety and ideal treatment duration of an adjuvant epidermal growth factor receptor tyrosine kinase inhibitor (EGFR-TKI) for patients with resected EGFR-mutated non-small-cell lung cancer (NSCLC) were not known until 2014, when this study was initiated." (PMID 40866342, 2025). "Non-small cell lung cancer (NSCLC) associated with epidermal growth factor receptor (EGFR) mutations has experienced notable therapeutic advancements; however, exon 20 insertion mutations continue to pose a significant challenge, demonstrating resistance to conventional EGFR inhibitors." (PMID 40390745, 2025). "Epidermal growth factor receptor (EGFR), a tyrosine kinase receptor regulating cell proliferation, survival, and migration, is frequently mutated or overexpressed in various tumors, especially in non-small cell lung cancer (NSCLC), driving tumor progression and therapy resistance." (PMID 40724826, 2025). "Although a small number of cancer patients can benefit from EGFR inhibitors as monotherapy in patients with malignancies such as breast cancer and non-small cell lung cancer, cancer cells may activate different mechanisms to evade the antitumor activity of EGFR-targeted anti-tumor drugs." (PMID 38751788, 2024). "The Roche cobas EGFR Mutation Test v2 (Roche Molecular Diagnostics, Pleasanton, CA, USA), an RT-PCR test approved by the U.S. Food and Drug Administration as a companion diagnostic tool for EGFR-TKI therapy for advanced non-small cell lung cancer, is the most popular testing platform in Taiwan." (PMID 38687753, 2024). "Mechanistically, in non-small cell lung cancer, mutations in EGFR lead to destabilization of the nonactive conformation of the EGFR protein and continuous activation of its kinase domain, which leads to continuous autophosphorylation of the C-terminal tyrosine site and results in tumorigenesis." (PMID 39777265, 2024). "The interaction between MET and EGFR significantly contributes to the progression and drug resistance in non-small cell lung carcinoma (NSCLC)." (PMID 39769452, 2024). "Finally, we found that three active ingredients (ferulic acid, luteolin, and quercetin) could inhibit the proliferation of non-small cell lung cancer cells and decrease the protein expression of EGFR in a concentration-dependent manner." (PMID 39628999, 2024). "This study aimed to determine whether the combined use of bevacizumab could improve overall survival (OS) in patients with brain metastasis (BM), epidermal growth factor receptor (EGFR)-mutant non-small cell lung cancer (NSCLC) undergoing cerebral radiotherapy." (PMID 38478262, 2024). "Tailoring therapeutic strategies for advanced non-small-cell lung carcinoma (NSCLC) relies on identifying specific biomarkers, such as programmed death ligand 1 (PD-L1) expression in tumor cells and the presence of oncogenic addictions like epidermal growth factor receptor (EGFR) mutations." (PMID 39509381, 2024). "EAI045 was successfully labeled with tritium and carbon-11, and the in vivo results indicated [11C]EAI045 may be able to distinguish between mutated and non-mutated EGFR in non-small cell lung cancer mouse models." (PMID 38363422, 2024). "EGFR/ErbB2 signaling pathway has been reported as important target in various kinds of cancer, including breast cancer, head and neck cancer, gastric cancer, pancreatic cancer, colon cancer, renal cell carcinoma, glioblastoma and non-small cell lung cancer, etc." (PMID 39075515, 2024). "Dacomitinib, a second-generation irreversible EGFR inhibitor, which has been found to be successful in the treatment of non-small-cell lung cancer, reached phase II trials in patients with recurrent glioblastoma patients with EGFR amplification with or without EGFR variants." (PMID 38396993, 2024).
non-small cell lung carcinoma (continued). "The epidermal growth factor receptor (EGFR) can recruit mitogen-activated protein kinase kinase kinase 3 (MEKK3) in a tumor necrosis factor receptor (TNF-R)-associated factor 4 (TRAF4)-dependent manner, which activates ERK5 and supports the proliferation of non-small-cell lung cancer cells." (PMID 38785963, 2024). "CHECKMATE 816 was the first phase 3 study to evaluate neoadjuvant nivolumab plus chemotherapy in patients with resectable stage IB–IIIA non-small cell lung cancer (per the AJCC seventh edition staging system) with no epidermal growth factor receptor (EGFR)/ALK mutations." (PMID 38731161, 2024). "HCC827 (EGFR mutated non-small-cell lung cancer: NSCLC) and H3122 (ALK+ NSCLC) cells did not respond to the FM, whereas SKBR3 (HER2+ breast cancer), BT474 (HER2+ breast cancer), and HCT116 (colorectal cancer) cells were responsive to it, showing reduced cell viability." (PMID 38999849, 2024). "Furthermore, a phase I trial tested the combination of hydroxychloroquine and erlotinib, an epidermal growth factor receptor (EGFR) tyrosine kinase inhibitor, in EGFR-mutant non-small cell lung cancer; it demonstrated preliminary activity and acceptable tolerability." (PMID 38850326, 2024). "EGFR inhibition can lead to the enrichment of the cancer stem cell subpopulation in non-small cell lung cancer, whether mutated or non-mutated in EGFR, through a NOTCH3-dependent process." (PMID 37444584, 2023). "Since these pathways both mediate PD-L1 expression and are associated with primary resistance to EGFR-TKI, we conducted this study to identify the key pathway that may impact the inconsistency in the prognostic value of PD-L1 in advanced non-small cell lung cancer patients treated with EGFR-TKIs." (PMID 36894581, 2023). "Evaluation of key driver mutations, such as those found in the genes encoding EGFR, anaplastic lymphoma kinase (ALK), and ROS proto-oncogene 1 (ROS1), has now become routine practice in the diagnostic pipeline of individuals with advanced non-small cell lung cancer (NSCLC)." (PMID 38144524, 2023). "We aimed to examine whether patients with de novo and relapsed/progressed stage IIIB–IV non-small cell lung cancer (NSCLC) without epidermal growth factor receptor (EGFR) or anaplastic lymphoma kinase (ALK) mutations have different prognoses." (PMID 37248452, 2023). "It remains controversial whether sarcopenia has any significant impact on the efficacy of epidermal growth factor receptor tyrosine kinase inhibitors (EGFR-TKIs) or immune checkpoint inhibitors (ICIs) in patients with advanced non-small cell lung cancer (NSCLC)." (PMID 36969820, 2023). "In addition, CNS metastases develop in around half of patients with mutant epidermal growth factor receptor (EGFR) or anaplastic lymphoma kinase-rearranged non-small-cell lung cancer, suggesting these genetic alterations are involved in neurotropic secondary tumors." (PMID 37688612, 2023). "In non-small cell lung carcinoma (NSCLC), targeted therapies are mainly directed toward specific altered genes that have been thoroughly analyzed, including EGFR, ALK, ROS1, and RET." (PMID 37999148, 2023). "In patients with advanced non-small-cell lung cancer (NSCLC) with EGFR oncogene addiction, osimertinib is an irreversible, third-generation EGFR tyrosine kinase inhibitor that is extremely selective for EGFR-activating mutations as well as the EGFR T790M mutation." (PMID 36831009, 2023). "In this review, we provide an overview of EGFR tyrosine kinase inhibitors (TKIs) in non-small cell lung carcinoma (NSCLC) treatment and their challenges." (PMID 34319535, 2022). "Moreover, STRA6 polymorphisms are associated with epidermal growth factor receptor (EGFR) mutations and might be therapeutic targets for patients with non-small cell lung cancer." (PMID 35874675, 2022).
non-small cell lung carcinoma (continued). "Additionally, previous studies have reported that PI3K-AKT signaling pathways could be suppressed after downregulation of EGFR in glioma, pancreatic cancer, and non-small cell lung cancer." (PMID 35846125, 2022). "Additionally, overexpression of EGFR enhanced βIII-tubulin translation in both K-Ras wild type and mutant expressing cell lines, however non-small cell lung cancer associated EGFR mutations appeared to have no impact on βIII-tubulin translation." (PMID 35573698, 2022). "In non-small cell lung cancer, AT-101 selectively inhibited cell proliferation and induced apoptosis via targeting EGF receptor with L858R/T790M mutations, overcame EGFR tyrosine kinase inhibitor resistance, and enhanced gefitinib sensitivity in cancer cells with EGFR T790M mutations." (PMID 35215257, 2022). "For instance, hsa_circ_0000190 was reported to be overexpressed in non-small cell lung carcinoma (NSCLC) and promote NSCLC progression via activation of the EGFR/ERK pathway." (PMID 36038948, 2022). "Many previous studies have demonstrated that minor-frequency pretreatment T790M mutation (preT790M) could be detected by ultrasensitive methods in a considerable number of treatment-naïve, epidermal growth factor receptor (EGFR)-mutated, non-small cell lung cancer (NSCLC) cases." (PMID 35840951, 2022). "EGFR overexpression is found in various human malignancies, including BCa, and a few monoclonal antibody drugs have been invented to target its protein in breast cancer and non-small cell lung cancer, either approved by the Food and Drug Administration of the US or under clinical trials." (PMID 35910372, 2022). "The EGFR inhibitors, which are principally used in non-small cell lung cancers or breast cancers, may act on SARS-CoV-2 virus replication, whereas JAK2 inhibitors could act on SARS-CoV-2 cytokine storm because IL-6 and GM-CSF, which are stimulated in this infection, depend on JAK2 signaling." (PMID 34864885, 2022). "However, in a small percentage of the EGFR-treated population (3–15%), the patient’s tumor has a histological transformation from non-small cell lung cancer (NSCLC), adenocarcinoma in particular, to neuroendocrine differentiated histology, specifically small cell lung cancer (SCLC)." (PMID 35268520, 2022). "Therefore, it is imperative to find a potentially effective solution to the problem of acquired resistance to EGFR-TKI for patients with integrin-β3 positive non-small-cell lung cancer (NSCLC) by exploring novel downstream targets and action mechanisms of integrin β3." (PMID 35805163, 2022). "The College of American Pathologists and the Association of Molecular Pathology guidelines recommend EGFR, ALK and ROS1 gene tests as mandatory in non-small cell lung carcinoma(NSCLC)." (PMID 35446881, 2022). "Claudins, the integral tight junction proteins that regulate paracellular permeability and cell polarity, are frequently dysregulated in cancer; however, their roles in regulating EGFR tyrosine kinase inhibitors (EGFR-TKIs) resistance in non-small cell lung cancer (NSCLC) are unknown." (PMID 35301287, 2022). "More interestingly, an adaptive survival program is induced by EGFR inhibition, leading to rapid formation of the EGFR-tumor necrosis factor receptor-associated factor 2 (TRAF2)-receptor-interacting protein 1 (RIP1)-IKK complex to activate NF-κB in non-small cell lung cancer xenograft model." (PMID 36358633, 2022). "In addition, a previous study showed that knockdown of CMTM7 promotes the malignant potential of non-small cell lung cancer cells and activates the epidermal growth factor receptor/protein kinase B (EGFR/AKT) signaling pathway by decreasing EGFR internalization and degradation." (PMID 34294040, 2021).
non-small cell lung carcinoma (continued). "As a therapy for non-small-cell lung cancer (NSCLC), another study also supported the evaluation of SNX-5422, especially in cases where cancer was driven by c-Met amplification and mutated epidermal growth factor receptor (EGFR) forms that were resistant to EGFR inhibitors." (PMID 34366885, 2021). "The epidermal growth factor receptor (EGFR), a membrane-bound tyrosine kinase receptor, has been found to be a critical oncogene in promoting the tumorigenesis, mitogenesis, and tumor progression of various cancer types, including non-small cell lung cancer (NSCLC)." (PMID 34155348, 2021). "Indeed, Niederst and colleagues found that Rb was lost in 100% of tumor samples and cell lines derived from EGFR mutant non-small cell lung cancer patients harboring resistance to anti-EGFR tyrosine kinase inhibitors when small cell lung cancer (SCLC) characteristics are being acquired." (PMID 33809148, 2021). "This multicenter, retrospective study aimed to evaluate the efficacy of the combination treatment with apatinib and osimertinib in 39 patients with EGFR-mutant non-small cell lung carcinoma (NSCLC) who developed osimertinib resistance." (PMID 34026823, 2021). "In addition, TAZ also enhances angiogenesis in EGFR wild-type non-small cell lung cancer cells." (PMID 33499877, 2021). "For instance, TNBC patients bearing mutations in PIK3CA, AKT1, and ESR1, as well as EGFR amplifications, may be treated with different drugs to those that are used to treat other subtypes of breast cancer (BRCA) and Non-Small Cell Lung Cancer (NSCLS), respectively." (PMID 34680239, 2021). "Plasma DNA can be analyzed by approaches targeting specific tumor-associated genes (e.g., mutations in the EGFR gene in non-small cell lung carcinoma (NSCLC)) or non-targeted screening approaches such as array CGH, whole-genome sequencing, or exome sequencing)." (PMID 34572727, 2021). "Furthermore, we investigated the usefulness of the proposed framework in a real medical application by evaluating reproducible radiomics features to non-invasively predict epidermal growth factor receptor (EGFR) mutant status in non-small cell lung cancer (NSCLC) patients." (PMID 33681463, 2021). "In addition, never smokers with non-small cell lung cancer were significantly associated with EGFR mutations (p<0.001)." (PMID 33956842, 2021). "Besides platinum-based chemotherapy, no established treatment option exists for advanced non-small-cell lung cancer (NSCLC) patients with EGFR exon 20 (Ex20ins) insertion mutations." (PMID 33946594, 2021). "One group isolated CTCs using the CTC-Chip from 23 metastatic non-small cell lung carcinoma (NSCLC) patients with known EGFR mutant tumours who had all received treatment with tyrosine kinase inhibitors." (PMID 33652649, 2021). "To date, several small molecule EGFR tyrosine kinase inhibitors (TKIs) have shown clinical benefit in clinical trials and been approved for the treatment of malignancies, with especially dramatic improvements in the therapeutic outcomes in non-small cell lung cancer (NSCLC)." (PMID 33679419, 2021). "Moreover, a previous study has reported the rate of EGFR mutations in non-small cell lung cancer in never-smoking Asian patients to be 60.7%, while the rate of EGFR mutations in our study was only 20%." (PMID 33102221, 2020). "However, the original U.S. Food and Drug Administration approval was based on response rate and non-small cell lung cancer, regardless of EGFR mutation status." (PMID 32138779, 2020). "Our multi-omics analysis of aggressive, early-stage non-small cell lung cancer (NSCLC) revealed PHGDH, PSAT1 and especially SHMT2 as highly up-regulated compared to normal lung as a consequence of proteome remodelling, and showed PSPH gene amplification linked with EGFR." (PMID 32903271, 2020).